RNU6-646P (RNA, U6 small nuclear 646, pseudogene)
Gene: Small nuclear RNA gene on chromosome 3 (196,708,859 to 196,708,964, reverse strand). Ensembl gene ENSG00000201441.
Homologues: Orthologues: chimpanzee U6 (98% identical), guinea pig U6 (74% identical), rat LOC120100172 (74% identical). Paralogues in human: RNU6-116P (84% identical), RNU6-36P (84% identical), RNU6-609P (84% identical), RNU6-1 (83% identical), RNU6-1175P (83% identical), RNU6-11P (83% identical), RNU6-15P (83% identical), RNU6-2 (83% identical), RNU6-33P (83% identical), RNU6-371P (83% identical), RNU6-37P (83% identical), RNU6-3P (83% identical), and 1288 more.